EGF (epidermal growth factor)
Diseases named in the same sentence as EGF in open-access papers (continued):
Sharing a sentence is not in itself a finding about the gene and the disease.
tumor (continued). "In the context of an ex vivo organoid model, OAd5NULL-A20 CD16-EGFRscfvs and CD16scfv-EGF transduction results in NK cell-mediated death suggesting that a targeted virotherapy in conjunction with a CD16-EGFR BICA can effectively inhibit tumor cell growth." (PMID 40741595, 2025). "Activation of Ras/Raf/MEK/ERK and PI3K/AKT/mTOR pathways by EGF promotes tumor growth, while SRC facilitates invasion and metastasis by enhancing cytoskeletal reorganization." (PMID 40226632, 2025). "Dysregulation of the EGF/EGFR signaling pathway has been shown to contribute to tumor initiation and progression." (PMID 39759123, 2025). "EGF, on the other hand, plays a role in tumour progression by enhancing cell proliferation, survival, and migration, as it binds to the epidermal growth factor receptor (EGFR)." (PMID 40906384, 2025). "We further performed cytokine array analyses with tumor cells stimulated with EGF and found increased protein levels of G-CSF, GM-CSF, and CCL-1 in control cells compared to CMTM4 KD cells." (PMID 39948411, 2025). "We observed more potent tumor-suppressing effects of αOX40 in EGF-low PDXs than in EGF-high PDXs, with average tumor inhibition values of 39.08% versus 18.45%." (PMID 40026246, 2025). "Among the distinctively upregulated genes in low EGF treatment, we found genes related to anti-tumor immunity, sperm flagellar assembly, and mitogenesis (SLC6A6, DNAH17, DUOX1)." (PMID 39694501, 2025). "EGFR expression is notably upregulated in CRC tissues and, upon binding to EGF, activates intracellular signaling cascades involved in tumor cell polarization, proliferation, and autophagy." (PMID 40060193, 2025). "These high-stemness cells showed a more active signaling landscape, with pathways related to tumor invasion, metastasis, and immune evasion such as TGFβ and EGF signaling pathways." (PMID 40963856, 2025). "On the contrary, VSIG4 promoted macrophage M2 polarization and induced malignant progression of tumour cells by promoting M2 macrophage secretion of heparin‐bound epidermal growth factor." (PMID 40405491, 2025). "FBXW7 mutations reduce EGF dependency, enhance MAPK/EGFR signaling, promote proliferation, and confer resistance to anti-EGFR therapies, thereby driving tumor progression." (PMID 41373479, 2025). "To explore potential functional implications of CCL18 and EGF expression in the tumor microenvironment, we next investigated their potential roles in modulating the tumor immune microenvironment." (PMID 40692603, 2025). "EGF regulates proliferation and differentiation of breast epithelial cells and plays a pivotal role in tumor cell growth in breast cancer." (PMID 40707586, 2025). "IVIS imaging showed in vivo localization of PS targeting antibodies and the Gla-EGF fusion protein to the tumors at 24 and 48 hours after intraperitoneal injection, while Isotype antibody showed minimal tumor localization." (PMID 40391322, 2025). "Following PCZ treatment of tumor cells, an increase in EGF cell surface staining was observed, indicating a rise in the availability of cetuximab‐binding sites on the cell surface compared to untreated cells." (PMID 39560161, 2025). "Clinical studies have shown that treatment with CIMAvax-EGF can prolong OS, although its efficacy varies depending on the individual characteristics of the tumor and of the patient." (PMID 41303538, 2025). "The tumor cells respond to EGF-secreting macrophages by migrating towards them and secreting more CSF-1, therefore generating a paracrine loop." (PMID 40646332, 2025). "We treated two mice with EGF and detected significant luc activity at tumor sites (red arrows) in both groups at 15 min." (PMID 39789599, 2025). "The epithelial cell subgroup from the tumor tissues displayed the highest level of EGF expression compared with the other cell subgroups." (PMID 40026246, 2025).
tumor (continued). "TAMs are known to directly support tumor proliferation by expressing molecules including epidermal growth factor (EGF), TGF-β, and members of the fibroblast growth factor (FGF) family." (PMID 40380196, 2025). "Conversely, TAMs (specifically M2 macrophages) support tumor invasion by secreting mediators like MMPs and epidermal growth factor (EGF), promoting lymphatic intravasation and distant metastasis." (PMID 40647432, 2025). "Lgr5+ tumor stem cells trigger OX40 gene transcriptional activity specifically in tumor ECs via paracrine epidermal growth factor." (PMID 40026246, 2025). "The EGF secreted by TAMs promotes the intravasation of tumor cells into blood vessels, while VEGF triggers the disruption of the endothelial cell barrier by breaking intercellular adhesion junctions." (PMID 40933995, 2025). "Ad5NULL-A20 CD16scfv-EGF, although functional, exhibits a reduced level of cytotoxicity and tumor cell death in comparison to CD16-EGFRscfvs due to low expression levels in cells." (PMID 40741595, 2025). "Since HER2 lacks a known ligand, EGF helps to simulate EGFR stimulation in vivo within the tumor microenvironment and aiding in the study of Wnt pathway’s interaction with HER2." (PMID 40642068, 2025). "After reaching the front of the tumor, TAMs secrete epidermal growth factor (EGF) and other migration-promoting factors that promote cancer cell motility and extracellular matrix remodeling to facilitate tumor progression." (PMID 40940867, 2025). "In the tumor microenvironment, the M2-TAMs release many other cytokines to encourage tumor invasion, including M‐CSF, MMPs, and EGF." (PMID 40109347, 2025). "TBOs are grown in a Matrigel-based medium with N2, B27, EGF, and bFGF to examine tumor–brain microenvironment interactions, including invasion and resistance mechanisms." (PMID 40647519, 2025). "Heregulin treatment promoted tumor growth, while EGF induced a modest increase relative to controls." (PMID 41224124, 2025). "Microenvironmental factors from tumor or stromal cells such as tumor-associated macrophages (TAMs), CAFs, including fibroblast growth factors (FGF), TGF-β, EGF, and hepatocyte growth factor (HGF), contribute to cadherin switching." (PMID 40399946, 2025). "Building upon the observed differential expression of CCL18 and EGF across multiple tumor types, we next focused on evaluating their expression specifically within the context of BRCA." (PMID 40692603, 2025). "Tumor cells are stimulated to produce macrophage colony-stimulating factor (M-CSF), which, in turn, induces EGF release by macrophages, and the whole cycle continues." (PMID 41516258, 2025). "The cytokines TGF-β and EGF secreted by TAMs are involved in the metastasis of tumor cells via regulation of the Smad and MEK/ERK signaling pathways." (PMID 40943546, 2025). "IVIS imaging showed in vivo localization of PS targeting antibodies and the Gla-EGF fusion protein to the tumors at 24 and 48 h after intraperitoneal injection, while isotype antibody showed minimal tumor localization." (PMID 41198619, 2025). "Gefitinib (ZD1839) is a potent, selective, and orally active EGFR tyrosine kinase inhibitor that inhibits EGF-stimulated tumor cell growth by blocking EGF-induced EGFR autophosphorylation in tumor cells." (PMID 40041495, 2025). "The upregulation of CTHRC1 facilitates tumor invasion and migration via the epidermal growth factor (EGF) receptor/ERK1/2/AKT signaling pathway." (PMID 40369674, 2025). "HDAC6 also can deacetylate β-catenin at lysine 49 and inhibit β-catenin phosphorylation at serine 45, promote epidermal growth factor–induced β-catenin nuclear localization, and lead to tumor cell proliferation." (PMID 39736396, 2025). "This process results in the acetylation of H3 at Lys9 and the EGF-triggered transcription of cyclin D1 and c-Myc, which in turn enhances cyclin D1-driven cell cycle progression and tumor formation." (PMID 40057191, 2025).
tumor (continued). "TAM-derived epidermal growth factor (EGF) drives the formation of elongated tumor cell protrusions that augment invasion, reinforced by a CSF-1/EGF positive feedback loop that markedly amplifies metastatic behavior." (PMID 41058699, 2025). "This process increases the expression of VEGF, PDGF, basic fibroblast growth factor (bFGF), and epidermal growth factor (EGF) stored in platelet α-granules, ultimately fostering tumor angiogenesis and accelerating tumor progression." (PMID 40458729, 2025). "The impact of USP11 on EGFR signaling was validated using USP11-KO cells, which demonstrated reduced EGFR stability and in vivo tumorigenic effect, and diminished responses to EGF stimulation in migration, proliferation, and 3D tumor spheroid assays." (PMID 41419456, 2025). "Bidirectional signaling between TAMs and tumor cells, such as CSF-1/EGF loops, foster a pro-metastatic niche, while TAM-derived factors like TGF-β and PGE2 enhance cancer stem cell plasticity." (PMID 40422244, 2025). "Antagonistic effects such as inhibition of EGF-dependent receptor phosphorylation, cell proliferation and tumor growth have been described for various EGFR-specific biparatopic molecules." (PMID 40536585, 2025). "The PYCR1-overexpressing A549 cells treated with EGF or TLR agonists exhibited significantly larger tumor spheroids compared with mock-transfected cells." (PMID 41254241, 2025). "The in vivo efficacy was evaluated in mice with solid Ehrlich Ascites Carcinoma (EAC), focusing on tumor volume, oxidative stress, inflammatory cytokines, Epidermal Growth Factor (EGFR) expression biomarkers, and histopathological analysis." (PMID 41599143, 2025). "A key limitation is the absence of functional assays to directly demonstrate the roles of CCL18 and EGF in tumor development and progression." (PMID 40692603, 2025). "TAMs can also facilitate the intravasation and extravasation of tumor cells by releasing epidermal growth factor (EGF) and vascular endothelial growth factor (VEGF)." (PMID 40933995, 2025). "The tumor spheroid size increased in Ctrl A549 cells treated with EGF or TLR agonists, whereas spheroid size was significantly reduced in PYCR1-KO A549 cells treated under the same conditions." (PMID 41254241, 2025). "Cancer-associated fibroblasts and macrophages within the tumor stroma release several growth factors that induce the EMT, such as TGFβ1, PDGF, EGF, and HGF." (PMID 39941895, 2025). "The positive feedback between tumor cells and TAMs triggered tumor cells to secrete CSF-1, stimulating TAMs to secrete epidermal growth factor (EGF), which also accelerated tumor invasion and metastasis by destroying the matrix 118-120." (PMID 40083710, 2025). "Mechanistically, leucine-rich repeat–containing GPCR5 (Lgr5+ ) cancer stem cells induced OX40 expression in tumor ECs via EGF/STAT3 signaling." (PMID 40026246, 2025). "By producing tumor-promoting growth factors, such as epidermal growth factor (EGF), transforming growth factor beta (TGF-β), chemokines, and the ECM, CAFs contribute to angiogenesis and metastasis of the tumor cells." (PMID 39904885, 2025). "In vivo, treatment with the nanoemulsion led to a marked reduction in tumor volume and weight, further linked to decreased serum levels of EGF and VEGF, which are critical factors in tumor growth and angiogenesis." (PMID 41303330, 2025). "Stromal cells move primarily in response to physical forces exerted by surrounding cells, while tumour cells are also subject to chemotactic forces, which direct their movement up spatial gradients of EGF." (PMID 40762719, 2025). "This paracrine loop, mediated by tumor cell-secreted CSF-1 and macrophage-secreted EGF, is critical in facilitating the co-migration of tumor cells and macrophages toward blood vessels." (PMID 40547026, 2025). "CIMAvax-EGF aims to stimulate the patient immune system to produce antibodies against EGF, thereby reducing the stimulation of tumor growth." (PMID 41303538, 2025).
tumor (continued). "These signaling events create a chemotactic axis in which the CSF-1/EGF signals become amplified, allowing the tumor cells and macrophages to remain in close proximity with each other as they migrate together as cell pairs (a process called streaming)." (PMID 40646332, 2025). "EGF’s role in regulating cell growth and differentiation highlights the complexity of signaling pathways that influence tumor behavior." (PMID 40227503, 2025). "Clinically, EGF levels were markedly higher in the sera and tumor tissues of patients with CRC than in their corresponding controls." (PMID 40026246, 2025). "Given prior studies implicating USP8 in EGFR ubiquitination, we evaluated EGFR immunoprecipitation following corticotroph tumor EGF-treatment." (PMID 40386408, 2025). "We further examined the role of PYCR1 in 3D tumor spheroid formation under EGF and TLR agonist treatment." (PMID 41254241, 2025). "The cytokines TGF-β and EGF secreted by tumor cells are involved in the metastasis of tumor cells via the regulation of the Smad and MEK/ERK signaling pathways." (PMID 40943546, 2025). "Meanwhile, the contrasting correlations of EGF—particularly its inverse relationship with M1 macrophages—highlight its likely contribution to an immunosuppressive tumor microenvironment." (PMID 40692603, 2025). "Tumor antigens are in turn targeted via binding to either MICA via NKG2Drp or EGFR via EGFR scfv or epidermal growth factor (EGF) ligand." (PMID 40741595, 2025). "HIF-1α triggers the production of pro-angiogenic factors like VEGF, promoting new blood vessel formation, as well as transcription activation of TGF-β3 and epidermal growth factor (EGF) to facilitate tumor metastasis to oxygen-rich tissues." (PMID 39735667, 2025). "EGF levels were significantly elevated in HCC tissues, and the activation of EGF/EGFR signaling correlated with aggressive tumor characteristics and intrahepatic metastasis." (PMID 38816668, 2024). "The combination of TGFβ and EGF is a potent inducer of cytoskeletal reorganization and tumor cell migration." (PMID 38760173, 2024). "The epidermal growth factor (EGF) is a known tumor promoting factor and has been used as chemoattractant in migration assays." (PMID 39369027, 2024). "Epidermal growth factor (EGF), which has a crucial role in tumor invasiveness, is produced, in part, by TAMs." (PMID 38920716, 2024). "Our in vivo results indicate that the inhibition of HIFs by FM19G11, as well as its downstream effectors of the pathway, VEGF/VEGFR1 autocrine loop, and EGF/EGFR autocrine loop markedly reduced tumor growth as well as the expansion of the EpCAM+/ABCG2+ cells." (PMID 39963656, 2024). "These molecules, including interleukins, interferons, tumor necrosis factors, chemokines, and growth factors like TGF-β, VEGF, and EGF, can promote or inhibit tumor growth, influence the tumor microenvironment, and impact the efficacy of cancer treatments." (PMID 39034318, 2024). "They support tumour cell survival in the peritoneal fluid by secreting epidermal growth factor (EGF) and hepatocyte growth factor (HGF)." (PMID 38783165, 2024). "Taken together, our results suggest that phosphorylation of FilGAP downstream of EGF-signaling plays a critical role in regulating chemotactic tumor cell migration by controlling cell–matrix adhesion and protrusion formation." (PMID 38426123, 2024). "EGF has a role in cancer progression, as its tyrosine kinase activity is responsible for tumor survival, growth, and metastasis." (PMID 38673560, 2024). "As can be seen from the Figure, C1 SRSF7+ MCs subtype had higher expression as a ‘sender’ in the EGF signaling pathway, whereas tumor-cells were acting as ‘receiver’, ‘mediator’ and ‘influencer’ in this signaling pathway." (PMID 39430754, 2024). "Pro-tumor neutrophils secreted a variety of cytokines to sustain tumor growth, including epidermal growth factor (EGF), hepatocyte growth factor (HGF), and platelet-derived growth factor (PDGF)." (PMID 39061147, 2024).
tumor (continued). "The results clearly showed that the stimulation of tumor promoters, such as EGF and bFGF, increased anchorage-independent cell transformation and cancer cell colony growth in cGAS-wt overexpressing cells compared to that of cGAS-mt overexpressing cells." (PMID 39424777, 2024). "We further validated the expression of EGFR by IF staining, showing EGFR staining primarily in HNF4A+ regions, underscoring the critical role of EGF signaling in fetal tumor cells." (PMID 39567475, 2024). "Tumor-promoting factors, including IL-4, EGF, and TGF-β, induced HES1 expression, but Rbpj knockdown attenuated these responses in both murine and human macrophage cell lines." (PMID 39702544, 2024). "CSF1 secreted by tumor cells both recruits macrophages to the tumor microenvironment and promotes macrophage expression of EGF." (PMID 39555068, 2024). "The first member of the TGF-β subfamily was described in 1981 as an element induced by epidermal growth factor (EGF) and capable of stimulating the transformation of fibroblasts into a tumor phenotype." (PMID 38672279, 2024). "For instance, the tumor suppressor Merlin activates the Hippo pathway but is negatively regulated by epidermal growth factor (EGF), leading to YAP/TAZ activation and promoting cancer growth and invasion." (PMID 39431199, 2024). "An autocrine relationship occurred among tumor cells, marked by the concurrent secretion of epidermal growth factor (EGF) and the expression of Erbb3 receptors." (PMID 39519201, 2024). "Our results demonstrate that the tumor produces TSLP when stimulated with epidermal growth factor (EGF) in both the U251 cell line and the GBM biopsy (GBM-b)." (PMID 38557942, 2024). "Our research findings suggest that High_NMBRS_Epitheial_cells have a closer interaction with stromal cells and immune cells in the tumor microenvironment and play stronger regulators and influencers in EGF signaling, VEGF signaling, and MK signaling." (PMID 39845190, 2024). "On the one hand, M2 macrophages have obvious immunosuppressive function to mediate immune escape and promote the proliferation and metastasis of THCA; on the other hand, it can also secrete VEGF and EGF to promote tumor microangiogenesis." (PMID 39568815, 2024). "M-CSF can induce TAMs to differentiate towards the M2 phenotype, thereby promoting the migration of tumor cells by secreting various cytokines such as epidermal growth factor (EGF), TNFs, and ILs." (PMID 38646440, 2024). "The association of EpCAM with pathways like PI3K/AKT signaling and its regulation by factors such as EGF via ERK1/2 signaling elucidates its part in tumor progression and resistance mechanisms." (PMID 39033780, 2024). "Particularly under M-CSF regulation, TAMs promote angiogenesis and tumor cell proliferation by secreting VEGF and EGF, creating a favorable microenvironment for tumor progression." (PMID 38646440, 2024). "Subsequent studies have shown that this gene is inhibited by EGF in breast cancer, promoting extracellular matrix invasion in vitro and tumor metastasis in vivo." (PMID 39334363, 2024). "Identified in a screening for tumor suppressor genes and present in low levels in normal cells, S100-A2 is stimulated in keratinocytes by epidermal growth factor." (PMID 38473953, 2024). "Through the paracrine loop involving CSF-1R and epidermal growth factor, this mechanism enhances the interaction between tumor cells and macrophages, further promoting the migration and infiltration of tumor cells." (PMID 38646440, 2024). "A key observation is that stimulating macrophages by CSF-1 and tumor cells by EGF induce podosomes and invadopodia formation, respectively, which can mediate basement membrane and tissue invasion of tumor cells." (PMID 39003350, 2024). "In parallel, tumor samples were evaluated for two growth factors protein expression (EGF and VEGF – as ligand and signaling initiators)." (PMID 38636197, 2024).